IGFBP7-AS1 (IGFBP7 antisense RNA 1)
Gene: Long non-coding RNA gene on chromosome 4 (57,109,736 to 57,207,459, forward strand). Ensembl gene ENSG00000245067.
Diseases named in the same sentence as IGFBP7-AS1 in open-access papers:
IGFBP7-AS1 is named in the same sentence as 1 disease in open-access papers, as found by Europe PMC text mining. Sharing a sentence is not in itself a finding about the gene and the disease. The quoted sentences say what the papers report.
tumor (1 paper, 2022). "IGFBP7 Antisense RNA 1 (IGFBP7-AS1) was identified as the key eRNA for its expression patterns of low levels in tumor tissues and favorable prognostic value in UCEC correlated with its target gene IGFBP7." (PMID 35836132, 2022).